CTDP1 (CTD phosphatase subunit 1)
Description:
Processively dephosphorylates 'Ser-2' and 'Ser-5' of the heptad repeats YSPTSPS in the C-terminal domain of the largest RNA polymerase II subunit. This promotes the activity of RNA polymerase II. Plays a role in the exit from mitosis by dephosphorylating crucial mitotic substrates (USP44, CDC20 and WEE1) that are required for M-phase-promoting factor (MPF)/CDK1 inactivation.
Synonyms: FCP1; CCFDN
Tractability: PROTAC: ubiquitination databases record sites on it; its protein half-life has been measured.
Gene: Protein-coding gene on chromosome 18 (79,679,803 to 79,754,503, forward strand). Ensembl gene ENSG00000060069.
Subcellular location: Nucleus; Cytoplasm, cytoskeleton, microtubule organizing center, centrosome; Cytoplasm, cytoskeleton, spindle pole; Midbody
Subcellular location (Human Protein Atlas): Nucleoplasm; Vesicles
Pathways (Reactome):
Disease: Abortive elongation of HIV-1 transcript in the absence of Tat; Formation of HIV elongation complex in the absence of HIV Tat; Formation of HIV-1 elongation complex containing HIV-1 Tat; Formation of the HIV-1 Early Elongation Complex; HIV elongation arrest and recovery; Pausing and recovery of HIV elongation; Pausing and recovery of Tat-mediated HIV elongation; Tat-mediated HIV elongation arrest and recovery; Tat-mediated elongation of the HIV-1 transcript
Gene expression (Transcription): Formation of RNA Pol II elongation complex; Formation of the Early Elongation Complex; RNA Polymerase II Pre-transcription Events; RNA Polymerase II Transcription Elongation
Gene Ontology:
Molecular function: protein binding; RNA polymerase II CTD heptapeptide repeat phosphatase activity; Tat protein binding; TFIIF-class transcription factor complex binding; phosphoprotein phosphatase activity; protein serine/threonine phosphatase activity
Biological process: exit from mitosis; host-mediated activation of viral transcription; protein dephosphorylation; transcription elongation by RNA polymerase II; negative regulation of cell growth involved in cardiac muscle cell development; regulation of transcription by RNA polymerase II
Cellular component: centrosome; midbody; nucleoplasm; nucleus; protein-containing complex; spindle; spindle midzone; spindle pole
Genetic constraint (gnomAD): Loss-of-function variants: 42 observed, 83.61 expected, observed/expected ratio (o/e) 0.5, 90% interval 0.39 to 0.65. The upper end of that interval is the gene's LOEUF score, 0.65, which puts it in group 2 of 6, group 1 being the genes least tolerant of losing a copy. Missense variants: 1,163 observed, 1,242.9 expected, observed/expected ratio (o/e) 0.94, 90% interval 0.89 to 0.98. Synonymous variants: 593 observed, 531.59 expected, observed/expected ratio (o/e) 1.12, 90% interval 1.04 to 1.19.
Homologues: Orthologues: chimpanzee CTDP1 (99% identical), macaque CTDP1 (80% identical), guinea pig CTDP1 (80% identical), rat Ctdp1 (79% identical), mouse Ctdp1 (78% identical), dog CTDP1 (76% identical), pig CTDP1 (75% identical), tropical clawed frog ctdp1 (60% identical), rabbit CTDP1 (59% identical), zebrafish ctdp1 (58% identical), Drosophila melanogaster Fcp1 (29% identical), Caenorhabditis elegans fcp-1 (23% identical).
Diseases named in the same sentence as CTDP1 in open-access papers:
CTDP1 is named in the same sentence as 24 diseases in open-access papers, as found by Europe PMC text mining. Sharing a sentence is not in itself a finding about the gene and the disease. The quoted sentences say what the papers report.
congenital cataracts (7 papers, 2016 to 2025). "CTDP1 gene (OMIM#604927) has been associated with congenital cataracts, facial dysmorphism, and neuropathy." (PMID 37296475, 2023). "A known pathogenic founder CTDP1 variant c.863+389C>T in a homozygous state was identified in the other family member confirming the suspected diagnosis of congenital cataracts, facial dysmorphism, and demyelinating neuropathy syndrome." (PMID 32454992, 2020). "Mutations in CTDP1 gene are associated with congenital cataracts, facial dysmorphism and neuropathy syndrome (CCFDN)." (PMID 27448395, 2016). "CTDP1 plays a crucial role in transcription regulation, RNA splicing, and genome integrity, and its dysfunction leads to the complex phenotype characterized by congenital cataracts, facial dysmorphism, and progressive neuropathy." (PMID 41515914, 2025). "Congenital Cataracts, Facial Dysmorphism, and Neuropathy (CCFDN) Syndrome is a rare autosomal recessive disorder caused by the deep intronic variant c.863+389C>T (or IVS6+389C>T) in the Carboxy-Terminal Domain phosphatase subunit 1 (CTDP1) gene." (PMID 41515914, 2025). "Congenital cataracts, facial dysmorphism, and neuropathy (CCFDN; OMIM #604168) is a unique syndrome, observed only in the Roma population, caused by a single nucleotide substitution in intron 6 of the C-terminal domain (CTD) phosphatase subunit 1 (CTDP1) gene." (PMID 32454992, 2020).
breast carcinoma (6 papers, 2019 to 2025). "In humans, a splice site mutation in CTDP1 gives rise to the rare Congenital Cataracts Facial Dysmorphism and Neuropathy syndrome, and recent evidence from our lab indicates CTDP1 is required for breast cancer growth and proliferation." (PMID 33408128, 2021). "CTDP1 transcript expression is elevated in breast cancer samples compared to normal tissues in TCGA data queried through UALCAN36." (PMID 31240132, 2019). "CTDP1 depletion in vitro and in vivo diminishes tumorigenic potential of breast cancer models, which is also consistent with previous findings in gastric and lung cancer in vitro experiments." (PMID 31240132, 2019). "Normal breast-derived MCF-10A and ER-positive MCF-7 breast cancer cells exhibit a reduction of CTDP1 expression in response to melphalan." (PMID 31240132, 2019). "To further validate CTDP1 as a potential target to sensitize breast cancer cells to chemotherapy, we sought to evaluate the impact of targeted deletion or depletion of CTDP1 expression on breast cell line growth." (PMID 31240132, 2019). "Increased CTDP1 expression occurs in stage 1 breast cancer and maintained through stage 4, and is elevated in both luminal and triple-negative subclasses." (PMID 31240132, 2019). "In addition, CTDP1 expression is necessary for breast cancer cell line growth both in vitro and in vivo." (PMID 31240132, 2019). "Breast cancer survival in the TCGA dataset was not significantly affected by CTDP1 expression (p = 0.52), but a separate database assembled by PRECOG37 of 16 different breast cancer studies determined that elevated CTDP1 expression correlates with decreased survival (z-score = 2.2, p = 0.028)." (PMID 31240132, 2019). "However, T-47D and MCF-7 breast cancer cell lines display reduced growth rates when CTDP1 is knocked down." (PMID 31240132, 2019). "In addition, CTDP1 knockdown interfered with the development of breast cancer cell lines, both in vitro and in vivo, underscoring the roles of CTDP1 as a regulator of genome stability and revealing its potential as a therapeutic target in cancer or diseases with impaired DNA damage repair." (PMID 41515914, 2025). "Indeed, a recent study by our lab found that CTDP1 knockdown not only increases the sensitivity of breast cell lines to DNA inter-strand crosslink (ICL)-inducing agents but also compromises the growth of breast cancer cells in vitro and in vivo." (PMID 33408128, 2021). "In addition, CTDP1 knockdown impairs in vitro and in vivo growth of breast cancer cell lines." (PMID 31240132, 2019). "Among them, 18 genes were essential for cancer cell proliferation, such as NSF for breast cancer, CCND1 for renal cell cancer, DHX16 for lung cancer, CDC27 for ovarian cancer, and CTDP1 for prostate cancer." (PMID 39025880, 2024). "Together, these results suggest that CTDP1 plays an important role in the regulation of the ICL repair pathway and reveal that it may be a promising therapeutic target for breast cancer." (PMID 31240132, 2019).
neuropathy (6 papers, 2017 to 2025). A disorder affecting the nervous system that manifests with pain, tingling, numbness, and/or muscle weakness. "Congenital Cataracts, Facial Dysmorphism, and Neuropathy (CCFDN) is a rare disorder caused by pathogenic or likely pathogenic genetic variants of the CTDP1 gene." (PMID 41515914, 2025). "CTDP1 has been associated with congenital cataract, facial dysmorphism, and neuropathy (OMIM#604168) phenotypes." (PMID 33815474, 2021). "A single point mutation in CTDP1 was identified as the cause of a diverse phenotype in the Vlax Roma population, including congenital cataracts, facial dysmorphisms, and neuropathy, referred to as CCFDN (Congenital Cataracts, Facial Dysmorphism, and Neuropathy) syndrome." (PMID 36313552, 2022). "While CTDP1 disease-causing variant is classically known as the genetic basis of CCFDN, genetic epidemiology studies in neuropathy cohorts have identified CTDP1 disease-causing variants in a small subset of patients diagnosed with CMT, particularly within demyelinating CMT1 subtypes." (PMID 41515914, 2025). "Congenital Cataracts, Facial Dysmorphism, and Neuropathy (CCFDN) syndrome is a rare autosomal recessive disorder predominantly found among Vlax Roma populations, caused by a deep intronic founder variant in the CTDP1 gene." (PMID 41515914, 2025).
Behcet disease (2 papers, 2020 to 2025). A chronic, relapsing, multisystemic vasculitis characterized by mucocutaneous lesions, as well as articular, vascular, ocular and central nervous system manifestations. "A proteome-wide autoantibody screening has identified CTDP1 as a novel autoantigen highly specific to Behcet disease, an autoimmune systemic vasculitis, highlighting CTDP1’s multifaceted biological roles beyond inherited disorders." (PMID 41515914, 2025). "Anti-CTDP1 autoantibodies exhibit high specificity for Behcet disease diagnosis and may influence tissues with rapid metabolism such as mucosa and skin." (PMID 41515914, 2025).
Congenital cataracts - facial dysmorphism - neuropathy (2 papers, 2008 to 2019). "However, mutation of human CTDP1 is associated with the rare congenital cataracts facial dysmorphism neuropathy (CCFDN) syndrome." (PMID 31240132, 2019). "In addition, a single-nucleotide substitution in an antisense Alu element in intron 6 of CTDP1 causes congenital cataracts facial dysmorphism neuropathy (CCFDN) syndrome." (PMID 19008958, 2008).
Fanconi anemia (2 papers, 2019 to 2025). Fanconi anemia (FA) is a hereditary DNA repair disorder characterized by progressive pancytopenia with bone marrow failure, variable congenital malformations and predisposition to develop hematological or solid tumors. "This BRCT domain facilitates CTDP1’s interaction with key DNA repair proteins, including those involved in the pathway of Fanconi anemia, thereby playing an essential role in maintaining genome integrity and coordinating transcription with DNA repair processes." (PMID 41515914, 2025).
ovarian carcinoma (2 papers, 2019 to 2024). A malignant neoplasm originating from the surface ovarian epithelium. "Breast cell lines were chosen for analysis in this study on CTDP1 because a subset of BRCT domain-containing proteins are known hereditary breast and ovarian cancer susceptibility genes, such as BRCA1 and BRCA234." (PMID 31240132, 2019).
brain cancer (1 paper, 2025). A primary or metastatic malignant neoplasm affecting the brain. "Among the other transcription factors that we found among colon transcriptomics features Irx2, Pou4f1, Pou6f1, Tfap2a, Ctdp1, and Msx1 are known to be involved in neuronal development or closely related processes 31–37, and Fubp1 in brain cancer." (PMID 40791429, 2025).
Charcot-Marie-Tooth disease (1 paper, 2025). An inherited degenerative disorder involving the peripheral nerves. "In addition, studies have expanded the phenotypic spectrum of CTDP1 causing variants to include contributions to Charcot-Marie-Tooth disease (CMT)." (PMID 41515914, 2025).
gastric cancer (1 paper, 2025). A primary or metastatic malignant neoplasm involving the stomach. "The inhibition of CTDP1 led to lower rates of proliferation in neoplastic cells, interruption of cell cycle at G0/G1 phase, as well as an enhanced apoptosis of gastric cancer cells." (PMID 41515914, 2025). "Other studies investigated the role of CTDP1 in cancer and oncogenesis, for example through exposing gastric cancer cells to lentivirus-mediated small interfering RNA (siRNA) in order to silence CTDP1 expression." (PMID 41515914, 2025). "When combined, these findings show that CTDP1 plays a major role in tumor growth, making it a promising therapeutic target for the treatment of gastric cancer." (PMID 41515914, 2025). "Moreover, CTDP1 knockdown has also inhibited the capacity of gastric cancer cells to form colonies." (PMID 41515914, 2025).
Hypercholesterolemia (1 paper, 2021). An increased concentration of cholesterol in the blood. "Case 5 (19ZC161) has four missense variants, including rs751141, in the hydrolase EPHX2 gene, associated with hypercholesterolemia (OMIM#143890), and rs761270780, in the CTDP1 gene." (PMID 33815474, 2021).
triple-negative breast carcinoma (1 paper, 2019). An invasive breast carcinoma which is negative for expression of estrogen receptor (ER), progesterone receptor (PR), and human epidermal growth factor receptor 2 (HER2). "The induction of FANCI S556 phosphorylation by CTDP1 overexpression was confirmed using the triple-negative breast cancer cell line MDA-MB-231 but was lower in signal intensity than the experiments performed in 293FT cells." (PMID 31240132, 2019).
cancer (6 papers, 2014 to 2025). A tumor composed of atypical neoplastic, often pleomorphic cells that invade other tissues. "Advances in molecular understanding have highlighted CTDP1’s diverse biological functions, its involvement in DNA repair and cancer biology, and its emerging role as an autoimmune biomarker." (PMID 41515914, 2025). "CTDP1 expression across a panel of seven breast cell lines revealed that 5/6 cancer lines maintained their CTDP1 expression following ICL damage with melphalan." (PMID 31240132, 2019). "The MDA-MB-231 and MCF-7 cancer cell lines were subjected to CTDP1 knockdown and then injected into the mammary fat pad of immunodeficient mice to evaluate in vivo growth." (PMID 31240132, 2019). "Information available from Depmap.org indicates that CTDP1 is a “common essential” gene because CRISPR-mediated knockout of this gene significantly reduced cell viability in 505 out of 517 cancer cell lines tested." (PMID 31240132, 2019). "A risk model based on Cox and LASSO regression analyses was made, showing that both AQP5 and CTDP1 have a significant impact on the prognosis of cancer patients, indicating that they may be used as prognostic markers." (PMID 41515914, 2025). "These experiments provide evidence that CTDP1 expression modifies HR efficiency, which could affect the response of cancers to DNA damage-inducing therapies." (PMID 31240132, 2019). "lncRNA-H19 and circular MYLK as well as circular CTDP1 could regulate the expression of DNMT3B, HAS3, VEGFA and ITGB1 through competing miRNA response elements (MREs) of miRNA-29a-3p, which would result in growth and metastasis of cancer." (PMID 27363013, 2016).
tumor (1 paper, 2025). "The analysis of a gene regulatory network focused on the immune microenvironment showed a positive correlation between AQP5/CTDP1 and immune cell infiltration into the tumor site." (PMID 41515914, 2025).
CTDP1 also shares sentences with these, for which no sentence is quoted: lung carcinoma (2 papers); cataract (1); Chronic colitis (1); colitis (1); Facial Dysmorphism, and (1); Immunodeficiency (1); infection (1); malaria (1); prostate carcinoma (1); renal cell cancer (1).